ASCL1 (achaete-scute family bHLH transcription factor 1)
Description:
Transcription factor that plays a key role in neuronal differentiation: acts as a pioneer transcription factor, accessing closed chromatin to allow other factors to bind and activate neural pathways. Directly binds the E box motif (5'-CANNTG-3') on promoters and promotes transcription of neuronal genes. The combination of three transcription factors, ASCL1, POU3F2/BRN2 and MYT1L, is sufficient to reprogram fibroblasts and other somatic cells into induced neuronal (iN) cells in vitro. Plays a role at early stages of development of specific neural lineages in most regions of the CNS, and of several lineages in the PNS. Essential for the generation of olfactory and autonomic neurons. Acts synergistically with FOXN4 to specify the identity of V2b neurons rather than V2a from bipotential p2 progenitors during spinal cord neurogenesis, probably through DLL4-NOTCH signaling activation. Involved in the regulation of neuroendocrine cell development in the glandular stomach (By similarity).
Synonyms: hASH1; bHLHa46; ASH1; MASH1
Tractability: No criterion of Open Targets' tractability assessment is met for any kind of drug.
Gene: Protein-coding gene on chromosome 12 (102,957,674 to 102,960,513, forward strand). Ensembl gene ENSG00000139352.
Subcellular location: Nucleus
Subcellular location (Human Protein Atlas): Nucleoplasm; Cytosol
Pathways (Reactome):
Signal Transduction: NGF-stimulated transcription
Gene Ontology:
Molecular function: bHLH transcription factor binding; DNA-binding transcription factor activity; DNA-binding transcription repressor activity, RNA polymerase II-specific; E-box binding; nucleic acid binding; protein binding; RNA polymerase II cis-regulatory region sequence-specific DNA binding; sequence-specific double-stranded DNA binding; DNA-binding transcription factor activity, RNA polymerase II-specific; RNA polymerase II transcription regulatory region sequence-specific DNA binding; chromatin binding; double-stranded DNA binding; identical protein binding; protein dimerization activity; sequence-specific DNA binding
Biological process: cerebral cortex GABAergic interneuron differentiation; negative regulation of apoptotic process; negative regulation of DNA-templated transcription; negative regulation of neuron differentiation; negative regulation of transcription by RNA polymerase II; neurogenesis; noradrenergic neuron fate commitment; Notch signaling pathway; positive regulation of transcription by RNA polymerase II; response to retinoic acid; lung epithelial cell differentiation; neuron development; neuron differentiation; neuron fate commitment; neuron fate specification; noradrenergic neuron development; positive regulation of neuron differentiation; regulation of gene expression; regulation of neurogenesis; sensory organ development; sympathetic ganglion development; sympathetic nervous system development; ventral spinal cord interneuron fate commitment; cellular response to magnetism; forebrain neuron differentiation; and 5 more
Cellular component: nucleus; chromatin; RNA polymerase II transcription regulator complex; neuronal cell body
Genetic constraint (gnomAD): Loss-of-function variants: 2 observed, 12.34 expected, observed/expected ratio (o/e) 0.16, 90% interval 0.065 to 0.51. The upper end of that interval is the gene's LOEUF score, 0.51, which puts it in group 2 of 6, group 1 being the genes least tolerant of losing a copy. Missense variants: 188 observed, 263.45 expected, observed/expected ratio (o/e) 0.71, 90% interval 0.63 to 0.81. Synonymous variants: 113 observed, 121.24 expected, observed/expected ratio (o/e) 0.93, 90% interval 0.8 to 1.09.
Homologues: Orthologues: macaque ASCL1 (99% identical), chimpanzee ASCL1 (98% identical), rat Ascl1 (96% identical), pig ASCL1 (95% identical), mouse Ascl1 (94% identical), guinea pig ASCL1 (86% identical), dog ASCL1 (85% identical), zebrafish ascl1a (72% identical), tropical clawed frog ascl1 (71% identical), tropical clawed frog ascl2 (36% identical), Drosophila melanogaster ase (25% identical), Drosophila melanogaster ac (20% identical). Paralogues in human: ASCL2 (40% identical), ASCL4 (23% identical), ASCL5 (22% identical), ASCL3 (18% identical).
Diseases named in the same sentence as ASCL1 in open-access papers:
ASCL1 is named in the same sentence as 117 diseases in open-access papers, as found by Europe PMC text mining. Sharing a sentence is not in itself a finding about the gene and the disease. The quoted sentences say what the papers report.
small cell lung carcinoma (51 papers, 2005 to 2025). Small cell lung cancer (SCLC) is a highly aggressive malignant neoplasm, accounting for 10-15% of lung cancer cases, characterized byrapid growth, and early metastasis. "Overexpression of ASCL1 has been implicated in the development of medullary thyroid cancer and small-cell lung cancer." (PMID 38673793, 2024). "Here, the authors discover that FOXA2, regulated by ASCL1, promotes multi-site metastasis in small cell lung cancer by inducing a fetal neuroendocrine gene expression program." (PMID 40419484, 2025). "ASCL1 is a transcription factor essential for neuroendocrine differentiation and is upregulated in several neuroendocrine tumors, including small cell lung cancer, where it promotes cell proliferation and survival." (PMID 40567599, 2025). "Molecular subtypes of small cell lung cancer (SCLC) have been described based on differential expression of the transcription factors (TFs) ASCL1, NEUROD1, and POU2F3 and immune-related genes." (PMID 40305287, 2025). "Alongside ASCL1, it significantly contributes to the promotion of malignant behavior and survival of human small cell lung carcinoma (SCLC) cell lines." (PMID 38674385, 2024). "Researchers used high-resolution tandem mass spectrometry to ascertain that IGF-BP5 is a specific secreted protein of ASCL1-high-expression small-cell lung cancer." (PMID 36832007, 2023). "In small cell lung cancer, ASCL1 has been identified as a downstream factor of BRN2 and has been implicated in the induction of RET kinase, however these pathways have not been proven in t-NEPC, yet." (PMID 35109899, 2022). "ASCL1 is one of the master transcription factors of small cell lung carcinoma and defines SCLC-A subtype—the most abundant representative of the subtype population in human SCLC." (PMID 35194152, 2022). "ASCL1 acts as an oncogene and/or tumour suppressor in a variety of other cancers including small cell lung cancer, glioblastoma, and advanced prostate cancer." (PMID 35366798, 2022). "Similar to NEPC, a subset of glioblastoma and small cell lung cancers are defined by elevated expression of ASCL1." (PMID 35477723, 2022). "Small cell lung cancer (SCLC) is a recalcitrant malignancy defined by subtypes on the basis of differential expression of the ASCL1, NEUROD1, and POU2F3 transcription factors." (PMID 35612556, 2022). "Small cell prostate cancer and small cell lung cancer exhibit transcriptional similarities including ASCL1 expression." (PMID 35109899, 2022). "Accordingly, the reactivation of Notch1 suppressed the growth of neuroendocrine lung tumors and small-cell lung cancer (SCLC) by ASCL1 downregulation in vivo and in vitro." (PMID 34680255, 2021). "We also wondered about the distribution of TRIT1 gene amplification according to the small-cell lung cancer molecular subtypes ASCL1, NEUROD1, POU2F3, and YAP1." (PMID 33919717, 2021). "Genome-wide fragmentation profiles across ~13,000 ASCL1 transcription factor binding sites distinguished individuals with small cell lung cancer from those with non-small cell lung cancer with high accuracy (AUC = 0.98)." (PMID 34417454, 2021). "ASCL1 expression is more highly expressed in neuroblastoma and small cell lung cancer cell lines than other cancer types in the CCLE database." (PMID 31819055, 2019). "Mis-expression of ASCL1 is correlated with small cell lung carcinomas with neuroendocrine features, while its constitutive expression in lung epithelial progenitor cells promotes remodeling and preneoplasia of pulmonary epithelium." (PMID 23114535, 2012). "Furthermore, NOTCH is known to suppress NE differentiation across various tissues, including in models of NEPC and ASCL1+ small cell lung cancer." (PMID 41509338, 2025). "miR-375 was upregulated in and correlated with ASCL1 levels in small-cell lung cancer cells." (PMID 38723001, 2024).
small cell lung carcinoma (continued). "In addition, JQ1 was found to mediate anticancer effect by downregulating the expression of Achaete-scute homolog 1 (ASCL1) in small-cell lung cancer." (PMID 35547880, 2022). "Small cell lung cancer (SCLC) has recently been characterized as heterogeneous tumors due to consensus nomenclature for distinct molecular subtypes on the basis of differential expression of four transcription markers (ASCL1, NEUROD1, POU2F3, and YAP1)." (PMID 35311069, 2022). "In small cell lung cancer lines, both gain-of-function and loss-of-function strategies have shown that POU3F2 regulates the expression of achaete-scute homolog-like 1 (ASCL1), which functions as a growth enhancer and helps tumor cells escape anti-cancer immune responses." (PMID 27271588, 2016). "In addition to being a key transcriptional regulator during embryogenesis and in adult stem cells, a role for ASCL1 has been demonstrated in a range of solid neuronal and neuroendocrine tumours such as glioblastoma, neuroblastoma, small cell lung cancer and prostate cancer." (PMID 35366798, 2022). "ASCL1 (also known as mASH1 or hASH1) is an activator-type pro-neural bHLH transcription factor of the neurogenin family that has been reported as overexpressed in neuroendocrine tumors of several malignancies, including in medullary thyroid cancer, small cell lung cancer and prostate cancer." (PMID 33572108, 2021). "KCTD16 is a transcriptional target of ASCL1, one of the master transcription factors of small cell lung carcinoma, (SCLC)." (PMID 34001146, 2021). "Thus, EZH2 promoted small cell lung cancer progression by suppressing the TGF-β-Smad-ASCL1 pathway." (PMID 27462425, 2015). "In small cell lung carcinoma, transcription factors such as NEUROD1, achaete-scute family bHLH transcription factor 1 (ASCL1), POU class 2 homeobox 3 (POU2F3), and Yes1-associated transcriptional regulator (YAP1) are used for sub-classification." (PMID 39937015, 2025). "Validation through qRT-PCR in 30 MTCs demonstrated upregulation of ASCL1, DLL3, and SOX2 in high-grade MTCs, a gene signature akin to small-cell lung carcinoma, molecular subgroup A. Subsequently, DLL3 expression was validated by immunohistochemistry." (PMID 38958823, 2024). "In small cell lung carcinoma (SCLC), BAP1 promotes oncogenic roles inducing the expression of ASCL1 (Achaete-Scute Family BHLH Transcription Factor 1), a key lineage-specific oncogenic driver in SCLC." (PMID 36318367, 2022). "(b) Heat map of the PEA3 family ETS transcription factors (ETV1, ETV4, and ETV5) and neuroendocrine transcription factors (ASCL1, NEUROD1, INSM1, and POU3F2 [BRN2]) in small cell lung cancer and lung adenocarcinoma cell lines." (PMID 34121659, 2021). "Achaete-scute family bHLH transcription factor 1 (ASCL1; also known as ASH1), a Smad-dependent target of TGF-β, was found to induce survival in small cell lung cancer cells." (PMID 27462425, 2015). "Small-cell lung cancer (SCLC) is an aggressive malignant cancer that is classified into four subtypes based on the expression of the following key transcription and co-transcription factors: ASCL1, NEUROD1, YAP1, and POU2F3." (PMID 33202998, 2020). "ASCL1 and CHGA have the same overexpression profile in small-cell lung cancer." (PMID 24360028, 2013). "ASCL1 and INSM1 serve as markers for neuroendocrine tumours, such as for small cell lung carcinoma (SCLC)." (PMID 40257984, 2025). "In small cell lung cancer, NOTCH inactivation leads to ASCL1-mediated upregulation of DARPP-32 and activation of AKT/ERK signaling that is likely independent of the EGFR-ERBB3 axis, suggesting that DARPP-32 may promote tumor cell survival through multiple mechanisms." (PMID 34675407, 2022).
small cell lung carcinoma (continued). "Despite recent progress in subtype classification for small cell lung carcinoma (SCLC), little is known about the biomarker for triple‐negative (ASCL1, NEUROD1, and POU2F3 negative) tumors." (PMID 37789961, 2023). "For comparison, we also collected EVs secreted by a non‐small cell lung cancer cell line (A549) and human bronchial epithelial cells (HBEC) as negative controls, as these cells lack ASCL1, NEUROD1, and POU2F3 expression." (PMID 40285610, 2025).
glioma (44 papers, 2011 to 2026). A benign or malignant brain and spinal cord tumor that arises from glial cells (astrocytes, oligodendrocytes, ependymal cells). "Ascl1 has also been implicated in Parkinson’s disease and various cancers (e.g., glioma and neuroblastoma)." (PMID 34173119, 2021). "We also show that the loss of ASCL1 significantly reduces the proliferation of GBMs induced in the brain of a genetically relevant glioma mouse model, resulting in extended survival times." (PMID 32573857, 2020). "To determine if the loss of ASCL1 altered the molecular profiles of the mouse glioma tumors, we carefully isolated tumor bulk from various regions of the brain from Ascl1WT (N = 5) and Ascl1CKO (N = 5) tumor mice for RNA‐seq analysis." (PMID 32573857, 2020). "Notably, high ASCL1 levels are linked to glioma stem cells (GSCs), which are characterised by increased proliferation, migration, and therapy resistance." (PMID 39457550, 2024). "In mice, loss of ASCL1 in glioma delays tumor progression thereby increasing survival." (PMID 34012965, 2021). "The frequency of these mutations is perhaps surprising since higher expression of ASCL1, Dll1, Notch1, -3, -4 have been shown to correlate with a higher glioma grade and poorer prognosis, implicating Notch signaling in more undifferentiated and aggressive tumor phenotypes." (PMID 31995621, 2020). "Endogenous levels of ASCL1 in glioma and glioblastoma are variable and tend to be higher in tumours of the ‘proneural’ class, characterized by neural progenitor cell (NPC) features." (PMID 40527452, 2025). "Re-expression of ASCL1 has been observed in several brain tumours, notably in a subset of gliomas and glioblastomas, implying either a direct developmental origin of the cancer cells or, more likely, a recapitulation of embryonic pathways." (PMID 40527452, 2025). "These two tumor types were specifically chosen because they contained “mixed glioma” cell types, co-expressed both ASCL1 and OLIG2, but exhibited completely different migratory behavior." (PMID 39609428, 2024). "ASCL1 is a transcription factor that promotes glioma tumorigenicity through interactions with Wnt and Notch signaling pathways." (PMID 35456993, 2022). "To investigate the potential role of ASCL1 phospho-regulation in glioma stem cells (GSCs), we first sought to determine ASCL1 expression in 4 cell lines derived from primary GBM tumors." (PMID 35149717, 2022). "Other BHLH family members are reported in cancer biology and clinical outcomes, especially brain cancers like ASCL1 in glioma and neuroblastoma, Olig2 in astrocytoma, and ATOH1 in medulloblastoma." (PMID 35806162, 2022). "The oncogenic environments of high grade GBM and lower grade gliomas are enriched for active Serine–Proline-directed kinases, such as CDKs22,23, which would maintain ASCL1 in a highly phosphorylated form in GBM cells." (PMID 35149717, 2022). "Genes associated with the neuronal differentiation pathway (Pcsk9, Runx1, Cebpb, Fzd4, Wnt7a, Ascl1, Fzd2, Edn3, Olig2, and Gpc2), gliomas (Shc1, Cdk4, E2f2, and Ccnd1), and cell cycle (Bub1b, Bub, Ccnb1, Ccnb2, and Cdc20) were significantly downregulated." (PMID 36147849, 2022). "In vitro experiments using cultured glioma cells have revealed ASCL1 is necessary for cellular proliferation via activation of WNT signaling." (PMID 34012965, 2021). "For example, high Ascl1 expression in glioma promotes neuronal differentiation and prevents tumor growth." (PMID 34173119, 2021). "For example, higher expression of Achaete-Scute Family BHLH Transcription Factor-1 (ASCL1), DLL1, Notch1, Notch3, Notch4, and Hey1 is associated with high-grade glioma and a worse prognosis." (PMID 36643842, 2021). "Not surprisingly, genome wide profiling revealed a critical role for ASCL1 in interacting with both Wnt and Notch signaling pathways to control the tumorigenicity of glioma cells in culture." (PMID 32573857, 2020).